AXIN1 (axin 1)
Diseases named in the same sentence as AXIN1 in open-access papers (continued):
Sharing a sentence is not in itself a finding about the gene and the disease.
liver cancer (22 papers, 2018 to 2026). An epithelial or non-epithelial malignant neoplasm that arises from the liver. "Here, we confirm that RGS-associated AXIN1 missense mutations are capable of driving Wnt/β-catenin signaling in liver cancer cells." (PMID 41550750, 2026). "Together, these data provide compelling evidence that AXIN1 RGS missense mutations induce Wnt/β-catenin pathway activation in liver cancer cells." (PMID 41550750, 2026). "Next, we examined how AXIN1 RGS missense cancer mutations impact Wnt/β-catenin signaling in a liver cancer background, using Huh7 cells." (PMID 41550750, 2026). "To address these issues, we introduced a variety of HCC-associated AXIN1 mutations as well as activating CTNNB1 mutations in the liver cancer cell line Huh7, HEK293T cells, and mouse liver progenitor organoids." (PMID 41550750, 2026). "AXIN1 is involved in the Wnt/β-catenin signaling pathway, and loss-of-function mutations in AXIN1 in liver cancer are associated with an enrichment of signals related to the cell cycle as well as a more aggressive phenotype." (PMID 37400777, 2023). "Patients with liver cancer harboring AXIN1 mutation may potentially derive therapeutic benefits from an alternative systemic treatment regimen devoid of immunotherapy." (PMID 39897920, 2025). "To assess how AXIN1-deficiency drives HCC, we introduced HCC-associated AXIN1 and CTNNB1 mutations in human liver cancer cells and liver-derived organoids." (PMID 41550750, 2026). "Mutations of HCC in the Wnt/β-catenin pathway frequently occur in HCC patients (~30% in CTNNB1 and ~10% in AXIN1) as well as multiple liver cancer cell lines." (PMID 31861402, 2019). "Correspondingly, AXIN1 overexpression exerts a suppressive effect on liver cancer." (PMID 38291457, 2024). "Liver cancer predominantly has mutations in CTNNB1 (25%) and AXIN1 (8%) genes." (PMID 36983771, 2023). "To test whether alternative translation initiation is physiologically relevant in the context of liver cancer, we evaluated AXIN1 expression in the HCC cell lines JHH5 and JHH6 that both harbor 5′ truncating mutations in exon 2 (Q6Rfs∗22 and E5Dfs∗2, respectively)." (PMID 41550750, 2026). "Additionally, SLC38A4 hinders liver cancer progression by preventing AXIN1 protein degradation." (PMID 38291457, 2024). "Although we and others have previously established a Wnt pathway-promoting role for missense mutations in the AXIN1 RGS domain, the physiological relevance of this mutation class in liver cancer has not been determined." (PMID 41550750, 2026).
liver cancer (continued). "For example, in WGD samples, the LOH of the cancer suppressor gene AXIN1 in chromosome 16p13.3 of liver cancer cells could lead to a poor prognosis, whereas it did not affect prognosis in nWGD samples." (PMID 37400777, 2023). "Similar to AXIN1, liver specific deletion of ARID1A alone could not initiate liver cancer in mice, albeit it enhanced diethylnitrosamine (DEN)-induced hepatocarcinogenesis." (PMID 35669430, 2022).
lung cancer (22 papers, 2013 to 2025). A malignant neoplasm involving the lung. "Mutations in AXIN1/2 genes have been proven to be related to hepatocellular carcinoma, prostate cancer and lung cancer." (PMID 34168671, 2021). "In summary, we showed that YTHDF2 deficiency inhibited lung cancer cell proliferation and migration by modulating m6A levels of AXIN1, and impeding the activation of Wnt/β-catenin signaling." (PMID 33980824, 2021). "Low Axin1 expression in lung cancer patients correlates with disease progression and a poor prognosis." (PMID 38534454, 2024). "For components of the destruction complex, AXIN1 methylation was found to correlate with radiosensitivity of lung cancer cells and clinical features of NSCLC." (PMID 38872189, 2024). "Distinct methylation statuses of the AXIN1 gene in lung cancer cells correlate with varying radio-sensitivities, highlighting the influence of methylation modifications on AXIN1 transcriptional levels." (PMID 38291457, 2024). "In this context, the inhibition of lung cancer cells induced by X-rays is potentially mediated through the upregulation of AXIN1." (PMID 38291457, 2024). "A previous study found that reduced expression of AXIN1 was related to poor differentiation of lung cancer." (PMID 35780128, 2022). "Knockout of AXIN1 sufficiently rescued the inhibitory effect of YTHDF2 depletion on lung cancer cell proliferation, colony-formation, and migration." (PMID 33980824, 2021). "NCB-0846, but not NCB-0970, inhibited the expression of TNIK as well as the expression of Wnt target gene products, including Axin1, Axin2 and cMyc, in A549 lung cancer cells." (PMID 33244122, 2021). "Additionally, we previously demonstrated that combinatorial treatment with metformin and pembrolizumab enhanced anti-tumor immunity in STK11 mutant lung cancer via axis inhibition protein 1 (AXIN1)-dependent inhibition of STING ubiquitination." (PMID 39308524, 2024). "X-ray-induced inhibition of lung cancer cells may be mediated by increasing the expression of Axin1 through genomic DNA demethylation and histone acetylation." (PMID 38534454, 2024). "Notably, lung cancer cells, characterized by distinct methylation statuses of the AXIN1 gene, demonstrate varying degrees of radiosensitivity." (PMID 38291457, 2024). "As STING activation is crucial for anti-cancer immune response, and we previously found that metformin enhanced the efficacy of immunotherapy in STK11 mutant lung cancer via AXIN1-based STING stabilization, whether the nucleotide compounds involved in the activation of STING were unknown." (PMID 39308524, 2024). "Furthermore, X-ray irradiation induces an elevation in AXIN1 expression and triggers apoptosis in lung cancer cells through the inhibition of histone deacetylase HDAC1/2, which potentially constituting one of the mechanisms underlying radiotherapy-induced tumor suppression." (PMID 38291457, 2024). "Therefore, AXIN1 may provide a new target for therapeutic intervention in lung cancer." (PMID 35780128, 2022). "As a RBP, RBM47 inhibits lung cancer growth and metastasis by inhibiting Nuclear Factor Erythroid-2 related Factor 2 (NRF2) activity and modulating AXIN1 mRNA stability." (PMID 35338124, 2022). "As expected, Knockdown of YTHDF2 increased the mRNA and protein levels of AXIN1 in A549 and H1792 lung cancer cells; whereas, the overexpression of YTHDF2 decreased the protein AXIN1 in A549 and H1792 cells." (PMID 33980824, 2021). "Individual treatments of a panel of human and murine lung cancer cell lines with the TNKS inhibitors XAV939 and IWR-1 dose-dependently repressed cell growth and increased cellular axin 1 and tankyrase levels." (PMID 23621985, 2013). "Therefore, AXIN-1-based STING stabilization was required for metformin to activate STING pathway and enhance immunotherapy efficacy in STK11 mutant lung cancer." (PMID 35281267, 2022).
lung cancer (continued). "Our finding that upregulated miR-128-3p in NSCLC cells simultaneously suppresses multiple negative regulators of β-catenin and TGF-β signalling, including Axin1, SFRP2, WIF1, SMURF2 and PP1c, provides unique insights in understanding the modulation of the β-catenin and TGF-β pathways in lung cancer." (PMID 28627514, 2017). "In the current study, we found that in STK11 mutant lung cancer without LKB1 expression, AXIN-1 served as a platform for binding with STING, which was enhanced by metformin treatment." (PMID 35281267, 2022).
colon carcinoma (18 papers, 2007 to 2025). "As malfunction of AXIN1 is implicated in many diseases, including for example colon cancer, identification of AXIN1 regulators could serve as novel therapeutic targets." (PMID 23331499, 2013). "This is the first work that we know of to use a mouse model system of Axin1-overexpression on the primary colon tumors to identify the effect of 5-HT1DR in metastasis." (PMID 26214021, 2015). "Axin-upregulated 1 (Axud1)/Cystein-serin-rich nuclear protein 1 (Csrnp1) is a putative tumor suppressor gene that is upregulated by exogenous Axin1 expression in a colon cancer cell line." (PMID 19732418, 2009). "During the course of our studies, the human orthologue of the gene, AXUD1, was identified in an array analysis of genes induced in a colon cancer cell line by over-expression of AXIN1." (PMID 17726538, 2007). "The ortholog of CSRNP-1, AXUD1, was previously identified as a gene that is up-regulated by over-expression of AXIN1 in a human colon cancer cell line." (PMID 17726538, 2007). "Overall, further investigation of the microbiota-Axin1 interactions will provide novel insights into the development of chronic diseases, e.g., IBD and colon cancer, and mechanistic strategies for therapeutic approaches." (PMID 38010886, 2023). "In contrast, small molecules such as IWR-3 and XV939 stabilize Axin1 and increase the β-catenin decomposition, thereby inhibiting proliferation of DLD-1 colon cancer cells." (PMID 32294900, 2020). "For example, a potential biomarker Axin1 was identifiable in just 10 ng of sample (protein extract of ∼1,000 HCT15 colon cancer cells)." (PMID 25222838, 2014).
melanoma (15 papers, 2007 to 2026). A malignant, usually aggressive tumor composed of atypical, neoplastic melanocytes. "In addition, Axin-1, a negative regulator of β-catenin, was also linked to tumor progression, including melanoma." (PMID 28212537, 2017). "Mutations in key WNT pathway genes APC, AXIN1, and CTNNB1 occur at low frequencies in melanoma (10, 2.9, and 5.9%, respectively, as reported by cBioPortal)." (PMID 41492362, 2026). "It was reported that Axin1 is a key mediator of cell apoptosis in human melanoma cells by inhibiting the BRAFV600E." (PMID 33582657, 2021). "In melanoma, frequencies of mutations in APC, AXIN1 and CTNNB1 are low, reaching according to cbioportal.org 10%, 2.9% and 5.9%, respectively, however, a significant interstudy variability exists." (PMID 32659938, 2020). "Our data showed that DAPT blockade in melanoma leads to the up-regulation of AXIN1, CSNK2A3, CEBPA2, CTNNB1, and c-myc genes in tumors." (PMID 32695658, 2020). "MEK inhibition has previously been shown to reduce the level of AXIN1 protein in melanoma cells, although the exact mechanism of ERK/MAPK regulation of AXIN1 needs further investigation." (PMID 30717152, 2019). "We find that itraconazole increases Gli-3, Axin-1 expression but decreases Gli-1, Gli-2, Axin-1, β-catenin, Wnt3A and Cyclin D1 expression in both melanoma cell lines when compared with untreated cells." (PMID 28212537, 2017). "To determine the effect of AXIN1 depletion on TRAIL-mediated apoptosis, we pre-treated melanoma cell lines with siRNA specific for AXIN1 prior to treatment with TRAIL and WNT3A CM." (PMID 23869245, 2013). "AXIN1-depleted cells were significantly more sensitive to TRAIL compared with control siRNA-treated cells across three distinct human melanoma cell lines." (PMID 23869245, 2013). "Unexpectedly, the depletion of AXIN1 significantly sensitized all melanoma cell lines to TRAIL, even those in which WNT3A was insufficient to sensitize cells to rhTRAIL." (PMID 23869245, 2013). "Moreover, elevating β-catenin signaling with the small molecule GSK-3 inhibitor CHIR99021 or by siRNA-mediated knockdown of a negative regulator of β-catenin, AXIN1, efficiently sensitized melanoma cells to rhTRAIL." (PMID 23869245, 2013). "Previously we have shown that AXIN1 levels are regulated by the ERK/MAPK signaling pathway in melanoma, and that depletion of AXIN1 by siRNA-mediated knockdown significantly sensitized multiple melanoma cell lines to apoptosis when treated with a targeted small molecule inhibitor of oncogenic BRAF." (PMID 23869245, 2013). "Our results suggest that targeted manipulation of these pathways in such a way as to decrease AXIN1 stability could also theoretically sensitize melanoma cells to TRAIL-based therapies." (PMID 23869245, 2013). "The mechanism involving combined BRAF inhibition and WNT/β‐catenin activation involved AXIN1 degradation and GSK3β inhibition, while hyperactivation of the MAPK/ERK pathway stabilized AXIN1 and consequently inhibited WNT signaling in melanoma." (PMID 41492362, 2026). "Additionally, AXIN1 expression was increased by HH044, leading to lower β-catenin levels and thus preventing the activation of canonical signaling implicated in increasing the expression of genes such as MITF and APE-1, which protect melanoma from cellular damage from reactive oxygen species." (PMID 40574005, 2025). "Apoptosis can be induced in M202 and M207 apoptosis-resistant NRAS-mutant melanoma lines by treatment with AZD6244, via Axin1 depletion." (PMID 34577571, 2021). "A drop in Axin1 levels was also observed to precede and be independent of apoptosis onset, significantly inhibiting tumor growth in melanoma mouse models induced by WNT3A and PLX4720." (PMID 34577571, 2021).
melanoma (continued). "We then confirmed the involvement of the Wnt/β-catenin signaling pathway by demonstrating that siRNA-mediated knockdown of an intracellular β-catenin antagonist, AXIN1, or treating cells with an inhibitor of GSK-3 also enhanced melanoma cell sensitivity to TRAIL." (PMID 23869245, 2013). "It was suggested that targeting Axin1 stability by post-translational modifications like phosphorylation by GSK-3β, PARsylation by tankyrase-1/2 (TNKS1/2), methylation by protein arginine methyltransferase 1 (PRMT1), and SUMOylation could sensitize melanoma cells to TRAIL-based therapies." (PMID 34577571, 2021).
lung adenocarcinoma (11 papers, 2021 to 2024). A carcinoma that arises from the lung and is characterized by the presence of malignant glandular epithelial cells. "YTHDF2 was upregulated in lung adenocarcinoma and was found to degrade axis inhibition protein 1 (AXIN1), which encodes a negative regulator of the Wnt/β-catenin signaling, eventually leading to Wnt/β-catenin activation and tumor progression." (PMID 38503745, 2024). "In multiple myeloma cells, YTHDF2 sustains proliferation through the STAT5A/MAP2K2/p-ERK pathway, while in lung adenocarcinoma cells, it promotes proliferation by targeting the AXIN1/WNT/β-catenin signalling pathway." (PMID 38397033, 2024). "The RNA m6A reader YTHDF2 targets AXIN1 and subsequently affects its stability to promote proliferation and metastasis of lung adenocarcinoma cells." (PMID 37366340, 2023). "Based on the TCGA data, we constructed a lung adenocarcinoma prognosis model, and we found five key Wnt signaling pathway related genes, including AXIN1, CTNNB1, LEF1, FZD2, FZD4." (PMID 36703749, 2022).
prostate carcinoma (10 papers, 2009 to 2025). A carcinoma that arises from epithelial cells of the prostate gland. "Several recent studies have detected AXIN1 gene sequence variations in subsets of ovarian endometrial adenocarcinomas and advanced prostate cancer, indicating new potentially relevant AXIN1 mutations." (PMID 31143301, 2019). "Although genetic alterations of APC, Axin1 and β-catenin have been detected in clinical specimens of advanced prostate cancer, the interaction between Axin1 and Wnt/β-catenin pathway in affecting prostate cancer progression is poorly understood." (PMID 38715121, 2024). "Correlation analysis showed that UBE2N protein expression was negatively correlated with Axin1 protein expression in patients with prostate cancer." (PMID 38715121, 2024). "Furthermore, Axin1 protein expression in prostate cancer tissue microarrays was also examined by IHC staining." (PMID 38715121, 2024). "However, few works have been conducted to clarify the role of UBE2N in Axin1 stability and Wnt/β-catenin pathway activation, especially in prostate cancer." (PMID 38715121, 2024). "Although genetic and epigenetic changes activate Wnt/β-catenin signaling to drive the progression of prostate cancer, it is not commonly observed for CTNNB1, APC, and AXIN1 genes to undergo mutations in prostate cancer." (PMID 38886806, 2024). "Additionally, UBE2N promotes the ubiquitination and degradation of Axin1, and the overexpression of Axin1 negates the effects of UBE2N on the viability and glycolysis of prostate cancer cells." (PMID 40771930, 2025). "Moreover, the Axin1 protein expression was also detected in DU145, LNCAP, PC3, and 22RV1 prostate cancer cell lines." (PMID 38715121, 2024). "Moreover, the annotated genes in the constructed network, such as APC, AXIN1, AKT2, CCND2, CAV1, TLE2 and TCF4, are essential regulatory components of these pathways in prostate cancer." (PMID 23782521, 2013). "For instance, 5% of prostate tumours harboured activating mutations in β-catenin, whereas changes in the coding region of Axin1 were recently identified in 6% of advanced prostate cancer and inactivating mutations in APC have not been found in prostate cancer patients." (PMID 19277043, 2009).